PODNL1 (podocan like 1)
Synonyms: SLRR5B; FLJ23447
Tractability: Antibody: UniProt places it where antibodies can reach, with medium confidence; UniProt predicts a signal peptide or a membrane-spanning region; its Gene Ontology location is reachable by antibodies, with medium confidence. PROTAC: its protein half-life has been measured.
Gene: Protein-coding gene on chromosome 19 (13,931,183 to 13,953,392, reverse strand). Ensembl gene ENSG00000132000.
Subcellular location: Secreted, extracellular space, extracellular matrix
Gene Ontology:
Molecular function: extracellular matrix structural constituent
Cellular component: extracellular matrix; gel phase of interstitial matrix
Genetic constraint (gnomAD): Loss-of-function variants: 50 observed, 38.59 expected, observed/expected ratio (o/e) 1.3, 90% interval 1.03 to 1.64. The synonymous counts are far from expectation, so gnomAD's model fits this gene poorly and the ratio says little. Missense variants: 788 observed, 668.14 expected, observed/expected ratio (o/e) 1.18, 90% interval 1.11 to 1.25. Synonymous variants: 406 observed, 306.67 expected, observed/expected ratio (o/e) 1.32, 90% interval 1.22 to 1.44.
Homologues: Orthologues: dog PODNL1 (90% identical), pig PODNL1 (88% identical), rat Podnl1 (82% identical), mouse Podnl1 (81% identical), guinea pig PODNL1 (79% identical), macaque PODNL1 (79% identical), chimpanzee PODNL1 (77% identical). Paralogues in human: PODN (49% identical), LRRC15 (22% identical), FLRT2 (20% identical), NYX (20% identical), FLRT3 (20% identical), FLRT1 (19% identical), LRRTM4 (17% identical), LRRTM1 (17% identical), LRRC4C (16% identical), LRRTM3 (16% identical), LRRC4B (15% identical), RTN4R (15% identical), and 10 more.